HDAC7 (histone deacetylase 7)
Diseases named in the same sentence as HDAC7 in open-access papers (continued):
Sharing a sentence is not in itself a finding about the gene and the disease.
pancreatic adenocarcinoma (3 papers, 2014 to 2023). "HDAC7 was found to be significantly associated with pancreatic adenocarcinomas, and this increased expression of HDAC7 discriminates pancreatic adenocarcinomas from other types of pancreatic tumours." (PMID 25322459, 2014). "Furthermore the quantitative method of HDAC7 and Nurr77 immunostaining clearly demonstrate that increased expression of both genes is associated with adenocarcinomas of the pancreas." (PMID 25275504, 2014). "It is difficult to determine at this stage whether upregulation of HDAC7/HDAC2/Nur77 in pancreatic adenocarcinomas is a cause or a consequence of malignant progression." (PMID 25275504, 2014). "In the present study, by using a new approach we provide evidence that several genes namely HDAC7, HDAC2 and Nur77 are overexpressed in significantly high percentage of pancreatic adenocarcinoma tumors compared to benign tumors and chronic pancreatitis." (PMID 25275504, 2014).
atherosclerosis (2 papers, 2011 to 2022). A disease characterized by the build-up of fatty material and calcium deposition in the arterial wall resulting in partial or complete occlusion of the arterial lumen. "Endou, Hdac7, Senp1, Olfr286, Olfr285, Nckap5l, Smarcd1, Lima1, Fam186a, and Espl1 are probable candidate genes for distal Chr15 atherosclerosis QTL (Ath53)." (PMID 36078077, 2022). "HDAC7 appears to be upregulated in mouse models of atherosclerosis, consistent with the very low expression of CCR7 in CD68+ cells from atherosclerotic plaques." (PMID 22163030, 2011). "Although HDAC7 mice are embryonic lethal, HADC6 deficient mice are viable and fertile, and it will be interesting to see in future studies if regression of atherosclerosis is impaired in HDAC6 deficient mice upon statin treatment." (PMID 22163030, 2011).
Burkitt lymphoma (2 papers, 2015 to 2017). A rare form of malignant mature B-cell non-Hodgkin lymphoma. "Here we report the loss of HDAC7 expression in cell lines established from B-ALL and Burkitt lymphoma as well as in pro-B-ALL samples from patients." (PMID 25675295, 2015). "We found that HDAC7 was underexpressed in the Burkitt lymphoma-derived Namalwa cell line." (PMID 25675295, 2015). "In contrast, HDAC7 has recently been reported to promote apoptosis of human pro-B-ALL and Burkitt lymphoma by down regulating c-Myc expression." (PMID 29126425, 2017).
chondrosarcoma (2 papers, 2018 to 2020). A malignant cartilaginous matrix-producing mesenchymal neoplasm arising from the bone and soft tissue. "OA cartilage exhibits elevated HDAC7 levels, whilst HDAC7 depletion in SW1353 human chondrosarcoma cells strongly suppressed IL-1-dependent induction of MMP13." (PMID 29652915, 2018). "Of note, the expression of HDAC2, HDAC7, and HDAC10 seemed to be increased in chondrosarcoma cell lines as compared to healthy human cartilage, and romidepsin targets one of these subtypes (i.e., HDAC2)." (PMID 33266275, 2020).
chromophobe carcinoma (2 papers, 2021 to 2025). "For example, in RCC (including chromophobe carcinoma, ccRCC, and papillary cell carcinoma), low expression of HDAC1, HDAC2, HDAC3, HDAC8, HDAC10 and high expression of HDAC5, HDAC7, HDAC11 have longer survival time." (PMID 34308568, 2021).
cognitive deficits (2 papers, 2023 to 2025). "Together, these data demonstrated that genetic knockdown of HDAC7 in astrocytes effectively ameliorated synaptic loss and cognitive deficits in PS19 mice." (PMID 39806423, 2025). "Genetic knockdown or pharmacological inhibition of HDAC7 ameliorated tau pathology, synaptic impairments and cognitive deficits in PS19 mice." (PMID 39806423, 2025). "Our study also found that reducing or inhibiting HDAC7 can alleviate synaptic impairments and cognitive deficits in PS19 mice, providing further support for the therapeutic potential of HDAC7 suppression in promoting astrocyte-mediated clearance of tau pathology." (PMID 39806423, 2025).
E. coli infection (2 papers, 2022 to 2024). "In mouse macrophages, HDAC7 was required for the increase in the NADPH/NADP+ ratio in response to Escherichia coli infection." (PMID 39373581, 2024). "Nicotinic acid could improve intestinal antimicrobial peptides to enhance resistance of weaned piglets to E. coli infection by regulating intestinal microflora and its metabolites, histone deacetylase SIRT1 and HDAC7, modification sites such as acH3K9, acH3K27, and pH3S10 in the promoter region." (PMID 35571917, 2022).
fibrosis (2 papers, 2021 to 2023). the formation of excess fibrous connective tissue in an organ or tissue in a reparative or reactive process. "HDAC7 might play a vital role in airway fibrosis and have the potential to be developed as a therapeutic target." (PMID 34011384, 2021). "HDAC7 might be essential to the pathogenesis of airway fibrosis." (PMID 34011384, 2021).
gastric tumor (2 papers, 2022 to 2023). "Finally, we determined the levels of K235 acetylation and ALKBH5, KAT8, and HDAC7 in ten pairs of matched fresh primary liver and gastric tumor samples and adjacent nontumor liver and gastric tissues." (PMID 37369679, 2023).
inflammatory bowel disease (2 papers, 2018 to 2023). A spectrum of small and large bowel inflammatory diseases of unknown etiology. "Indeed, common variant single nucleotide polymorphisms (SNPs) in the HDAC7 gene are significantly associated with human autoimmune and auto-inflammatory diseases, namely primary sclerosing cholangitis and inflammatory bowel disease." (PMID 29664401, 2018).
lymph node metastasis (2 papers, 2025 to 2026). "Furthermore, LUAD patients with deep tumour invasion and/or a high T stage (T3/T4), a high American Joint Committee on Cancer (AJCC) 8th edition stage (stage III-IV) and lymph node metastasis (N1-N3) had higher expression levels of HDAC7." (PMID 39990668, 2025). "HDAC7 is overexpressed in CRC tumors and correlates with advanced disease stages, lymph node metastasis, and poor patient survival." (PMID 42157949, 2026).
multiple myeloma (2 papers, 2021 to 2022). "In particular, panobinostat caused a substantial downregulation of HDAC7 as well as a significant upregulation of HDAC6 in myeloma cells." (PMID 34888496, 2021). "Together, these data indicate that reducing expression of HDAC7 in parental myeloma cells, which is a feature of panobinostat treatment, caused cell cycle alterations likely responsible for the observed reduction in cell growth." (PMID 34888496, 2021). "HDAC6 and HDAC7 protein expression was probed to determine if transcript changes were seen at the protein level in bortezomib-resistant myeloma cells." (PMID 34888496, 2021). "Surprisingly, we discovered HDAC6 and HDAC7 were upregulated and downregulated, respectively, in two separate models of bortezomib-resistant myeloma cells." (PMID 34888496, 2021). "We further examined HDAC7 expression before and after vorinostat or panobinostat treatment in wildtype and bortezomib-resistant myeloma cells individually." (PMID 34888496, 2021). "Interestingly, panobinostat treatment altered HDAC gene expression: HDAC7 was downregulated while HDAC6 was upregulated after panobinostat treatment in myeloma cell lines." (PMID 34888496, 2021). "Although we did not investigate the downstream targets of HDAC7 that may contribute to the decreased cell growth, HDAC7 regulates cyclin D1 expression in osteogenesis, and it is possible that this function of HDAC7 is conserved in myeloma." (PMID 34888496, 2021). "Decreased HDAC7 priming for cell death has been observed in neurons exposed to low potassium treatment, but not documented in myeloma." (PMID 34888496, 2021).
Obesity (2 papers, 2023 to 2026). Accumulation of substantial excess body fat. "Transgenic expression of Hdac7 in myeloid cells mimicked the hepatic inflammatory phenotype that was observed in mice fed a high fat, high cholesterol and high sucrose (HFHCHS) diet, an obesity model that mimics some features of metabolic dysfunction-associated steatotic liver disease." (PMID 42255101, 2026).
prostate carcinoma (2 papers, 2014 to 2024). A carcinoma that arises from epithelial cells of the prostate gland. "Additionally, HDAC7 was reported to affect epithelial–mesenchymal transition (EMT) pathway in prostate cancer." (PMID 38827027, 2024).
adenoma (1 paper, 2013). A neoplasm arising from the epithelium. "We performed a PCR array for HDAC1, HDAC2, HDAC3, HDAC5 and HDAC7 on human rectal biopsies from patients with or without an adenoma in the colon (n = 86 subjects total)." (PMID 23724067, 2013).
Adult onset (1 paper, 2023). Onset of disease manifestations in adulthood, defined here as at the age of 16 years or later. "Of the four genes harboring rare or low-frequency variants previously identified as associated with adult-onset MS, three (PRF1, NLRP8, and HDAC7) passed quality control and filtering steps to be included in analyses." (PMID 36755464, 2023).
age-related macular degeneration (1 paper, 2015). Age-related loss of vision in the central portion of the retina (macula), secondary to retinal degeneration. "Human neural retina concentrations of HDAC1, 2, HDAC5, HDAC6, and HDAC7 decreased in age-related macular degeneration (AMD)-affected donors and exhibited a greater decrease in AD-affected donors in comparison to age-matched control neural retinas." (PMID 25962138, 2015).
Anxiety (1 paper, 2025). Intense feelings of nervousness, tension, or panic often arise in response to interpersonal stresses. "The upregulation of HDAC7 in astrocytes triggers NF-κB activation, leading to inflammation and anxiety-like behaviors, while the downregulation of HDAC7 reverses these effects." (PMID 40940748, 2025).
asthma (1 paper, 2025). "Indeed, roles for other epigenetic effectors, including histone methylation and acetylation marks, have been implicated in the severity of asthma, and a genome-wide association study identified significant histone modifying enzyme (KDM2A, KDM4C, HDAC4, HDAC7 and HDAC9) polymorphisms in asthma." (PMID 40057553, 2025).
astrocytomas (1 paper, 2008). "The highest level of mRNA was observed for HDAC9a and HDAC9b, with relative expression reaching values above 100 for normal brain tissue and grade I astrocytomas; however, HDAC6 and HDAC7 showed levels of expression comparable with those of class I (approximately 1.0 and 3.0)." (PMID 18713462, 2008).
autoimmune liver disease (1 paper, 2018). "We hope that this effort will illuminate the way forward in translating our finding that reestablishing missing iNKT cells can ameliorate HDAC7-mediated hepatic autoimmunity into potential therapeutic modalities for the analogous human diseases, based on the restoration of innate effector function." (PMID 29664401, 2018).
B-cell lymphoma (1 paper, 2015). "Our findings strongly indicate that HDAC7 exerts a strong anti-oncogenic effect in pro-B-ALL and B-cell lymphoma." (PMID 25675295, 2015). "We present data demonstrating that the transcriptional repressor HDAC7 has a potent anti-oncogenic effect in particular types of B-ALL and B-cell lymphoma." (PMID 25675295, 2015). "Altogether, these data indicate that HDAC7 is deregulated in particular types of B-ALL and B-cell lymphoma." (PMID 25675295, 2015). "We demonstrated that the expression of a crucial HDAC, HDAC7, for B lymphocyte biology is lost in pro-B-ALL patients and in the B-ALL and B-cell lymphoma cell lines, and that its re-expression has a potent anti-oncogenic effect." (PMID 25675295, 2015). "The modulation of HDAC7 expression in specific types of B-ALL and B-cell lymphoma leading to the induction of apoptosis and the downregulation of the c-Myc oncogene may be a promising therapeutic pathway in future." (PMID 25675295, 2015). "Why is HDAC7 underexpressed in specific types of B-ALL and B-cell lymphoma?" (PMID 25675295, 2015). "Taken together, our findings suggest that HDAC7 expression may exert an anti-oncogenic activity in particular types of B-cell malignancies and that its deregulation may contribute to the pathogenesis of B-ALL and B-cell lymphoma." (PMID 25675295, 2015). "Thus, our in vivo data confirm that HDAC7 induces apoptosis and exerts a potent anti-oncogenic effect suggesting that its absence may be involved in the pathogenesis of specific types of B-ALL and B-cell lymphoma." (PMID 25675295, 2015).
bladder cancer (1 paper, 2020). "There are few reports on the role of IL-7 and HDAC7 in bladder cancer." (PMID 32655621, 2020).
cardiomyopathy (1 paper, 2022). A disease of the heart muscle or myocardium proper. "Sepsis-induced cardiomyopathy in blood mononuclear cells and cardiac tissue cells is stimulated by serum levels of biomarkers (hsa-miR-23a-3p, hsa-miR-317, and hsa-miR-23b-3), which alter neurovascular-related HDAC7/ACTN4 signaling pathways linked to the NF-κB pathway." (PMID 35756932, 2022).
chronic gastritis (1 paper, 2020). Inflammation of the stomach that is chronic in nature. "The down-regulation of NDUFS8 (NADH: Ubiquinone Oxidoreductase Core Subunit S8), MT2A (Metallothionein 2A), HDAC7 = Histone Deacetylase 7, and PDK1 (Pyruvate dehydrogenase kinase 1) in chronic gastritis and intestinal metaplasia, respectively, was also confirmed." (PMID 31897247, 2020).
coronary artery disease (1 paper, 2022). "A previous study reported a significant elevation in HDAC7 mRNA expression in the monocytes of patients with coronary artery disease." (PMID 35756932, 2022).
cyst (1 paper, 2020). A sac-like closed membranous structure that may be empty or contain fluid or amorphous material. "The HDAC7 expression level is up-regulated during the cyst formation and sexual reproduction stages." (PMID 32508886, 2020).
dementia (1 paper, 2024). Loss of intellectual abilities interfering with an individual's social and occupational functions. "HDAC7 is a kind of histone deacetylases, and some histone deacetylases are associated with memory impairment and dementia." (PMID 38167011, 2024).
dilated cardiomyopathy (1 paper, 2020). Cardiomyopathy which is characterized by dilation and contractile dysfunction of the left and right ventricles. "However, even if there is no concrete evidence of involvement of HDAC7 in heart failure, the lower level in pathological hmMSC, compared to the healthy cells, suggests vascular abnormalities seen in dilated cardiomyopathy." (PMID 32650632, 2020).
erythroleukemia (1 paper, 2024). Acute erythroid leukemia characterised by the presence of at least 50% erythroid precursors and at least 20% myeloblasts in the bone marrow. "Instead, we identified HDAC7 as a selective regulator in erythroleukemia." (PMID 39277669, 2024).
Hepatic fibrosis (1 paper, 2023). The presence of excessive fibrous connective tissue in the liver. "The capacity of CYLD to antagonise HDAC7‐mediated repression of HGF expression limited hepatic fibrosis, suggesting a potential role for HDAC7 as a switch that enables gene expression upon liver injury." (PMID 35303381, 2023).
high blood pressure (1 paper, 2022). "Moreover, concordant effects on high blood pressure were found at three loci, including SH2B3, CTF1 and HDAC7, consistent with the epidemiologic association of high blood pressure with increased IgA levels." (PMID 36369178, 2022).
ischemia (1 paper, 2025). A hypoperfusion of the BLOOD through an organ or tissue caused by a PATHOLOGIC CONSTRICTION or obstruction of its BLOOD VESSELS, or an absence of BLOOD CIRCULATION. "During ischemia, PDGF-BB stimulation induced QKI-6, promoting HDAC7 splicing, activation of SM22, and iPS-VSMC differentiation, thus demonstrating QKI-6 is critical for the modulation of HDAC7 splicing for regulating iPS-VSMCs differentiation and functionality." (PMID 41222726, 2025).
lentivirus infection (1 paper, 2025). Virus diseases caused by the Lentivirus genus. "Consistently, we regulated reversely HDAC7 in DNMT3a overexpression or knockdown LUAD cells by lentivirus infection, HDAC7 overexpression or knockdown could partially reverse the DNMT3a-induced c-Myc proteins changes, which was confirmed by western blotting." (PMID 39990668, 2025).
melanoma (1 paper, 2025). A malignant, usually aggressive tumor composed of atypical, neoplastic melanocytes. "Independent from vemurafenib resistance, the curcumin-harmine-isovanillin combination drug GZ17-6.02 upregulated class I MHCA and suppressed PD-L1 in PDX BRAFV600E melanoma cells, which was mediated by the downregulation of several HDACs (HDAC3, HDAC5, HDAC6, HDAC7, and HDAC8)." (PMID 39935431, 2025).
orchitis (1 paper, 2025). Inflammation of one or both testes due to viral or bacterial infections. "The orchitis-related testicular impairment could be exerted on Leydig cells, and TNF-α could serve as a histone deacetylase 7 activator." (PMID 41402910, 2025).
Osteopenia (1 paper, 2017). Osteopenia is a term to define bone density that is not normal but also not as low as osteoporosis. "Deletion of either Hdac7 or Hdac9 in BMMs resulted in enhanced osteoclast differentiation in vitro, and increased bone resorption and osteopenia in mice in vivo." (PMID 28953929, 2017).
primary sclerosing cholangitis (1 paper, 2018). "Additional common variant SNPs in kinases known to export Class IIA HDACs via phosphorylation, including SIK2 and PRKD2, are also associated with primary sclerosing cholangitis, suggesting aberrant regulation of HDAC7 nuclear export as a causative mechanism." (PMID 29664401, 2018).
protein misfolding diseases (1 paper, 2019). "Moreover, we found that SAHA treatment results in a significant reduction of HDAC7, a principle HDAC that mediates correction of NPC141, as well as other protein misfolding diseases such as cystic fibrosis and alpha-1 antitrypsin deficiency." (PMID 31699992, 2019).
psoriasis (1 paper, 2015). An autoimmune condition characterized by red, well-delineated plaques with silvery scales that are usually on the extensor surfaces and scalp. "HIF-1α and its regulators (HDAC-1, HDAC-7, VHL-E3, PHD2, LL-37, HIF-1β, mTOR, miR-210, RORγt, STAT3, and IL-13Ralpha, as well as glycolysis enzymes) could be important pharmacological targets to restore the lack of regulation in the angiogenesis and in immunological processes involved in psoriasis." (PMID 26136626, 2015).
psychosomatic disorders (1 paper, 2025). "This review first outlines how epigenetic dysregulation contributes to psychosomatic disorders through altered expression of genes such as GRM2, TRPA1, SLC6A4, NR3C1, leptin, BDNF, NAT15, HDAC4, PRKCA, RTN1, PRKG1, and HDAC7." (PMID 41439979, 2025).
retinal degeneration (1 paper, 2017). Degeneration of the retina. "Our transcriptomic data also revealed an increase in a number of non-apoptotic pathway genes that have been implicated in retinal degeneration, such as a number of poly-ADP-ribose-polymerases (PARP9, PARP14, PARP15) and histone deacetylases (HDAC7, HDAC10, HDAC11)." (PMID 29263354, 2017).
Sepsis (1 paper, 2022). Sepsis is defined as life-threatening organ dysfunction caused by a dysregulated host response to infection. "Gene set enrichment analysis was performed to examine the potential role of dysregulated HDAC7 in the progression of SIC based on the bulk RNA transcript data of patients with sepsis." (PMID 35756932, 2022). "In combination with sepsis-related DEmiRNAs, HDAC7/ACTN4 was identified as a key transcriptional regulatory pair in the progression of SIC and in monocyte regulation." (PMID 35756932, 2022). "Studies reporting on the role of HDAC7/ACTN4 in sepsis or SIC are limited." (PMID 35756932, 2022). "In addition, HDAC7/ACTN4 was upregulated in monocytes in patients with sepsis." (PMID 35756932, 2022).